MTOR (mechanistic target of rapamycin kinase)
Diseases named in the same sentence as MTOR in open-access papers (continued):
Sharing a sentence is not in itself a finding about the gene and the disease.
tumor (continued). "Finally, we mechanistically demonstrated that in vivo tumor growth suppression following mTOR inhibition in vivo is CD8 cell dependent." (PMID 26506415, 2015). "The PI3K/Akt/mTOR pathway in human tumor cells is often constitutively activated." (PMID 25854175, 2015). "Thus, the TGF-β1 and PTEN are two important tumor related proteins which all regulated PI3K/Akt/ mTOR pathways." (PMID 25793716, 2015). "Nonetheless, there is a large body of literature that indicates that mTOR inhibitors may be effective against various aspects of tumour development." (PMID 25699174, 2015). "Subsequent genome-wide microarray analyses revealed several significantly differentially regulated genes of which 13 with tumor-related functions (i.e. apoptosis, mTOR signaling, cell cycle regulation, directional cell movement) were selected for re-evaluation on RNA and protein level." (PMID 25888189, 2015). "In summary, this work provides the evidence supporting a unique metabolic mechanism by which tumor cells can quickly shift their major energy metabolism from the aerobic glycolysis to mitochondrial respiration by relocating mTOR to mitochondria and inhibiting HK II activity." (PMID 25807077, 2015). "This miRNA was found to inhibit tumor proliferation by suppression of mTOR." (PMID 25889518, 2015). "Activation of pathways of mTOR also may promote tumor growth and increase the activation of imflammatory cell pathways that may negatively impact the cardiovascular system." (PMID 26893937, 2015). "In this pathway, mTOR inhibitors show anti-tumor activity in HCC." (PMID 26561802, 2015). "Activation of mTOR has been shown to contribute in tumor growth and progression." (PMID 26020804, 2015). "However, anecdotal reports have described remarkable responses in salivary tumors when genetic aberrations and therapies were matched: trastuzumab and lapatinib for Her2-aberrant salivary tumors or mTOR inhibitors for PIK3CA-aberrant neoplasms." (PMID 26247885, 2015). "Indeed, combinatorial application of SCD1 small molecule inhibitor, A939572, with mTOR inhibitor, Temsirolimus, synergistically attenuated in vitro and in vivo tumor growth in advanced/metastatic ccRCC patients." (PMID 26210994, 2015). "In the current study, inhibition of 11ßHSD2 activity led to inhibition of lung tumorigenesis in KrasLA2 mice associated with COX-2 inhibition and increased ER stress as well as inhibition of the ERK and mTOR signaling pathways due to increased tumor cell active glucocorticoids." (PMID 26011146, 2015). "Our findings suggest a model in which simultaneous regulation of DAG and PA levels by DGKζ is integrated with mTOR function to maintain tumor cell homeostasis; we provide new evidence of the crosstalk between mTOR and lipid metabolism that will be advantageous in the design of drug therapies." (PMID 26302180, 2015). "Our data suggests that temporal inhibition of mTOR by rapamycin during early tumor development may result in persistent ER stress in tumors that develop long after rapamycin treatment." (PMID 26575021, 2015). "Such a glycolysis-associated MTOR signal cascade was validated in human HBV-related HCC tissues and shown to mediate the inhibitory effect of a model of combined resveratrol and silymarin product on tumor growth." (PMID 25909713, 2015). "Mechanically, we find that cav-1/AKT/mTOR pathways account for the anti-tumor effects of baicalein." (PMID 25957503, 2015). "However, the complex role of mTOR in regulating the energy balance of RCC tumor cells requires further efforts to better explain the effects of mTOR inhibition on tumor cell metabolism." (PMID 25885920, 2015). "While p-Akt(Ser473) has not convincingly been shown to be associated with prognosis, expression of its downstream target mTOR has been associated with tumor grade or worse prognosis, but this has not been found in all studies." (PMID 26793165, 2015). "The mammalian target of rapamycin (mTOR) is involved in many mechanisms of tumour progression." (PMID 26698305, 2015).
tumor (continued). "Inactivation of mTOR can promote p27 expression in various tumor tissues." (PMID 26500453, 2015). "Nevertheless, there is rising evidence that the mTOR-signaling pathway especially in case of recurrent GBM plays an important role in tumor relapse, as a recent study demonstrated a high rate of mutations of members of the mTOR-pathway after temozolomide treatment." (PMID 25993328, 2015). "The BCAAs then function to activate mTOR signalling and tumor cell proliferation." (PMID 26030804, 2015). "A dietary compound induced autophagy of tumor cells might help enhance mTOR inhibitors to accelerate tumor cell killing and thus herald a novel cancer therapy." (PMID 25945840, 2015). "Inhibition of the phosphoinositide 3 kinase pathway intermediate, mammalian target of rapamycin (mTOR), also inhibits tumor growth and may prevent escape from VEGF receptor inhibitors." (PMID 26295809, 2015). "However, this therapeutic approach is limited by the development of resistance of the tumor and microvasculature to the effect of rapalog mTOR inhibition." (PMID 26295809, 2015). "Likewise, tumor control by Sorafenib treatment can be significantly enhanced by co-administration of the mTOR inhibitor rapamycin or simultaneous use of TACE (transcatheter arterial chemombolization)." (PMID 26287667, 2015). "Multiple signaling pathways such as the mitogen-activated protein kinase/extracellular signal-regulated kinases (ERK), signal transducer and activator of transcription 3 (STAT3), and Akt/mammalian target of rapamycin (mTOR) pathways are involved in tumor biology." (PMID 25965999, 2015). "Among them, erythropoietin (EPO) may stimulate EMT in RCC via the PI3K/Akt/mTOR pathway in agreement with the observations that the mTOR inhibitor Everolimus was able to slow down RCC tumor growth and to reverse EMT phenotype in a mouse xenograft model." (PMID 26579493, 2015). "In fact, in disseminated tumor cells (DTC) PI3K/Akt signaling is reduced, thus suggesting that mTOR pathway inhibition might be linked to a biologic quiescence of DTC." (PMID 26468083, 2015). "However, the expressions of phospho-AKT at Ser473 and Thr308 and phospho-mTOR were decreased in the ES-2TR160 tumor cells with high expressions of HIN-1." (PMID 26497956, 2015). "Preclinical data showed that targeting mTOR along with antiandrogen treatment exhibited additive antitumor effects in a prostate-specific Pten (pseudogene of the tumor suppressor)-deleted mouse model, supporting the rationale for combining AR and mTOR inhibitors to treat CRPC." (PMID 26690121, 2015). "The mechanisms underlying these effects clearly need further attention, but our data indicate a strong inhibitory effect of PROG alone and in combination with TMZ on the EGFR/PI3K/Akt/mTOR signaling which promotes tumor cell proliferation and inhibits apoptosis." (PMID 26110872, 2015). "To test whether mTOR inhibitors, such as sirolimus, could suppress tumor growth in allograft mice as well, we treated the allograft mice with various concentrations of sirolimus." (PMID 26418749, 2015). "Thus, in two very different approaches, we find that SEMA3F administration (local and/or systemic) has similar anti-tumor and anti- angiogenesis effects by inhibiting the Akt/mTOR signaling pathway." (PMID 26156437, 2015). "Currently, therapeutic approaches for BHD renal tumorigenesis and other mTOR-related FLCN-deficient neoplasia have not yet been described." (PMID 26418749, 2015). "Thus, combined GLI1/2 and PI3K/mTOR inhibition represents a promising novel approach for synergistic apoptosis induction and tumor growth reduction with implications for new treatment strategies in RMS." (PMID 25749378, 2015). "Tumor cell death in response to mTOR inhibition is enhanced by the use of autophagy inhibitors." (PMID 26637440, 2015). "Thus, the identification of proteins whose silencing synergizes with mTOR inhibition to decrease tumor growth is of particular interest." (PMID 25834103, 2015).
tumor (continued). "In the ESCC tumor samples, mTOR protein was elevated by western blot analysis." (PMID 26357655, 2015). "Sorafenib inactivates ERK and mTOR signaling pathway and suppresses the tumor formation." (PMID 26556861, 2015). "The PI3K/Akt/mTOR signalling pathway mediates the multiple cellular and molecular functions through the altered expression of its targeted genes, which are critical to tumor initiation, progression and outcomes." (PMID 26022660, 2015). "Importantly, oral delivery of C-PAC significantly inhibited OE19 tumor xenograft growth via modulation of AKT/mTOR/MAPK signaling and induction of the autophagic form of LC3B supporting in vivo efficacy against EAC for the first time." (PMID 26378019, 2015). "GA treatment also inhibited tumor mammalian target of rapamycin (mTOR) signaling pathway." (PMID 26011146, 2015). "In human tumors, mTOR pathway appeared strongly activated with tumor stage." (PMID 26447612, 2015). "Rapamycin treatment inhibits cell proliferation and tumor growth by blocking mTOR signaling." (PMID 25909163, 2015). "We next hypothesized that MEK and mTOR inhibition may exert different effects on the development of adaptive immunity within the MOC tumor microenvironment." (PMID 26506415, 2015). "mTOR is known to suppress autophagy while promoting tumor cell growth, proliferation and survival." (PMID 25580621, 2015). "It seems that the effect of the cell biological function through inhibiting the expression of mTOR may vary with origins of tumors or depends on cellular characteristics of tumor cells." (PMID 25854175, 2015). "However, we found that PTEN expression, which exerts a suppressive effect over the PI3K/Akt/mTOR pathway, was decreased in advanced stage tumours, in accordance with previous observations." (PMID 26569621, 2015). "Indeed, lipid biosynthesis or lipid droplet formation plays a crucial role in cell proliferation and tumor growth, which tightly links to mTOR signaling." (PMID 26160839, 2015). "In addition, luciferase assays demonstrated that miR-99b-5p functioned as a tumor suppressor by targeting mTOR." (PMID 26259252, 2015). "However, the relative effects of investigational mTOR active-site inhibitory drugs on tumor cell growth, production of vascular growth factors, versus direct effects on the host vasculature in in vivo mouse xenograft models are difficult to determine." (PMID 26295809, 2015). "Strikingly, here we propose that the proliferative stroma with activated mTOR signaling could also be a good prognostic indicator of the tumor regressive process in a particular tumor context." (PMID 26098779, 2015). "In this context, it is worth noting that, in transplanted patients, some tumor types may show a regression if immunosuppressive therapy is withdrawn or changed/enriched with drugs such as mTOR inhibitors and mycophenolate." (PMID 26185750, 2015). "These dedifferentiated hepatocytes might be subsequently transformed by the activated PI3K/AKT/mTOR cascade, as the PI3K/AKT/mTOR pathway might provide the necessary cell proliferative and metabolic requirement for tumor formation." (PMID 25826091, 2015). "Such agent is expected to (a) activate mTOR and related pathway, (b) be a tumor-promoter." (PMID 25587030, 2014). "In fact, it has recently been demonstrated that long-term treatment with the mTOR inhibitor everolimus causes drug non-responsiveness, demonstrated by reactivation of the tumour growth and invasion program." (PMID 24779401, 2014). "Interestingly, there appears to be differential expression of mTOR depending on the primary tumor site." (PMID 25092520, 2014). "In this study, mTOR signaling was activated in both tumor and vascular ECs of SAS-R and SAS tumors." (PMID 24464839, 2014). "We found that tumours in KRAS PTEN mice exhibit a remarkable dependence on mTOR signalling." (PMID 24717934, 2014).
tumor (continued). "Taken together, these results suggest that by evading β-TRCP-mediated degradation, cells expressing the non-degradable version of NEDD4 (NEDD4-AA) have increased cell growth and cell migration, presumably through the activated mTOR/Akt pathway by suppressing the PTEN tumor suppressor." (PMID 24657926, 2014). "To address this issue, we analysed 12 cases with established EGFR mutation status for therapeutic purposes (each 6 cases with/without EGFR mutations) and evaluated the tumor specimens for hamartin, p-tuberin and p-mTOR expression." (PMID 24593867, 2014). "Interestingly, normal-like mucosa of MI lesions preserved p-mTOR expression in a significant proportion of cases that had lost it in the tumour sections." (PMID 25202348, 2014). "In the present group of MI tumours, two p-mTOR phenotypes were observed." (PMID 25202348, 2014). "Based on activation of the PI3K/mTOR pathway in a murine transgenic NB model expressing ALKF1174L and MYCN, we demonstrated that combining an ATP-competitive mTOR inhibitor with crizotinib induced tumor regression, although the molecular basis for this result was unclear at the time." (PMID 25228590, 2014). "As autophagy is required for the effective management of metabolic stress, promoting autophagy through mTOR pathway inhibition might be expected to limit tumor progression." (PMID 25389774, 2014). "For example, the activation of AMPK would stimulate increased glucose uptake, which in the presence of active mTOR signaling could then be shuttled into the pentose phosphate pathway to drive anabolic tumor processes." (PMID 24861463, 2014). "The correlation of survivin suppression and anti-tumor synergy found in our study suggest that survivin expression may be a good biomarker for treatment targeting the IGFR/PI3K/Akt/mTOR pathway." (PMID 24387108, 2014). "Interestingly, Fbw7 is often referred to as a tumor suppressor for its roles in regulating the degradation of potent oncogenes such as Cyclin E, c-Myc, c-Jun, Mcl-1, mTOR and Notch-1." (PMID 24912918, 2014). "mTOR and pmTOR were found to be expressed in the cell membrane and cytoplasm of tumor tissues." (PMID 25120661, 2014). "In the present study, only p-mTOR expression was evaluated in a cohort of 76 UBC tumours, which although may constitute a limitation, was analysed together with markers of blood and lymphatic endothelium." (PMID 25202348, 2014). "In the lean mice, leucine increased phosphorylation of mTOR and downstream effector S6 ribosomal protein, but in the overweight mice, leucine reduced glucose clearance and thus increased the amount of circulating glucose available to the tumor." (PMID 24685128, 2014). "Our data provide evidence that HLA-G may inhibit tumor cell proliferation through mTOR signaling blockade." (PMID 24800261, 2014). "It was also noted that the PI3K/Akt/mTOR pathway correlates with the resistance to chemotherapy based on the analysis of the correlation between the change of p-mTOR expression and the change of tumor size." (PMID 25364442, 2014). "The importance of using an agent to target the activated PI3K/AKT/mTOR pathway might be overestimated since tumor control might be induced by simultaneous inhibition of other key targets and/or processes by the combination regimens." (PMID 25426553, 2014). "Vice versa, disruption of the TSC tumor suppressor complex results in an upregulation of mTOR." (PMID 24593867, 2014). "Higher baseline tumor levels of phosphorylated mTOR predicted for better outcomes." (PMID 25092520, 2014). "In these tumours, mTOR inhibition leads to proliferative arrest and even tumour regression." (PMID 24717934, 2014). "Mutations were discovered in 23% of EC tumor, with PIK3CA/mTOR being the most frequently mutated." (PMID 24859412, 2014). "Many negative regulators of mTOR signaling are known human tumor suppressors." (PMID 25257528, 2014). "Vertical blockade of the IGFR/PI3K/Akt/mTOR pathway has promising anti-tumor activity for HCC." (PMID 24387108, 2014).
tumor (continued). "The potential synergy between the mTOR inhibitor, rapamycin, and icotinib may have contributed to the rapid remission of the tumor in the present case." (PMID 24348843, 2014). "The PI3K/AKT/mTOR pathway is a commonly activated pathway in multiple tumor types including HL." (PMID 24395633, 2014). "Obviously, the treated groups each showed significant growth inhibition compared to control group (P < 0.05 or < 0.01) during the same period, especially the mTOR siRNA + cisplatin group, indicating that mTOR siRNA combined with cisplatin has the strongest inhibition of tumor growth." (PMID 24818169, 2014). "Consistent with in silico predictions, mTOR inhibitor testing in our TNBC xenografts showed significant tumor growth inhibition in all, suggesting that mTOR inhibitors can be effective in TNBC, but will require use with additional therapies, warranting investigation of optimal drug combinations." (PMID 24708766, 2014). "However, the underlying mechanism of mTOR regulation of cell motility and mTOR inhibitors inhibiting tumor cell motility is controversial." (PMID 25003395, 2014). "IGF-1R is a receptor tyrosine kinase (RTK) that stimulates protein synthesis by activating the mammalian target of rapamycin (mTOR), and in turn mTOR mediated upregulation of glycolytic enzymes may promote tumor development." (PMID 25048361, 2014). "Dysregulation of mTOR signaling can be found in many tumor types, however in clinical trials inhibitors of mTOR so far show only modest results, which may be due to activation of the PI3K/Akt pathway." (PMID 25126409, 2014). "Owing to the fundamental role of PI3K/Akt/mTOR pathway in tumor development and progression, there has been a significant interest in developing inhibitors against components of this pathway, up to having now many compounds currently under evaluation in clinical trials." (PMID 25296981, 2014). "In addition to this, tumour cells should be specifically targeted with this course of treatment, due to the tumour cells oncogenic addiction to the PI3K/mTOR signalling pathway." (PMID 24909675, 2014). "Collectively, this data suggests that both AZD8055 and NVP-BEZ235 mono-therapy decreased tumor growth in LKB1−/−NIC mice, however the inhibition of mTOR by AZD8055 was significantly more effective at preventing tumor growth compared with NVP-BEZ235 treatment alone." (PMID 25436981, 2014). "In this context, the success of this combination therapy suggests both inhibition of the BRAF fusion protein by sorafenib and of the downstream mTOR pathway by temsirolimus synergizes, although the specific mechanism of tumor regression awaits further investigation." (PMID 24422672, 2014). "However, it has been suggested that chronic drug treatment creates undesired feedback loops, reactivating the Akt-mTOR pathway and enabling tumour cells to restart their growth program." (PMID 24779401, 2014). "Overall, evidence has been presented that HDAC-mTOR cross-linking exists in tumour cells, and combined application of an HDAC- and mTOR inhibitor might overcome limitations encountered with a mono-drug regime." (PMID 24779401, 2014). "Moreover, crosstalk of the mTOR pathway with other pathways gives rise to compensatory loops for tumor cells to escape anti-tumor stimuli." (PMID 24393708, 2014). "After treatment of the xenografts generated from primary tumors, overall decreased phosphorylation of these proteins suggested decreased mTOR pathway activity, which may have contributed to observed tumor growth inhibition." (PMID 24708766, 2014). "Analyses of tumor lysates by Western blot and IHC assays indicated that rapamycin greatly reduced the levels of S6 phosphorylation, consistent with rapamycin inhibition of the mTOR signaling." (PMID 24831086, 2014). "Considering the multiple inhibitory function of miR-100 on both IGF-1R and mTOR, we speculate that miR-100 may have more potent anti-tumor activity than mTOR inhibitors alone." (PMID 25026290, 2014).